HDAC7 (histone deacetylase 7)
Diseases named in the same sentence as HDAC7 in open-access papers (continued):
Sharing a sentence is not in itself a finding about the gene and the disease.
leukemia (8 papers, 2015 to 2025). A malignant (clonal) hematologic disorder, involving hematopoietic stem cells and characterized by the presence of primitive or atypical myeloid or lymphoid cells in the bone marrow and the blood. "Therefore, this novel therapy opens a new field for personalized treatments in high-risk leukemia, especially for infants presenting low expression of HDAC7 B cell factor." (PMID 40722046, 2025). "We speculate that the loss of HDAC7 expression in particular types of leukemia and lymphoma may be the result of the transcriptome changes induced by a specific primary lesion." (PMID 25675295, 2015). "Several mechanisms could account for the loss of HDAC7 expression in leukemia and lymphoma." (PMID 25675295, 2015). "On the other hand, HDAC7 that is mostly decreased in various types of leukemia can downregulate MYC." (PMID 34372899, 2021). "Contrary to other HDACs, HDAC7 which down-regulates MYC is mostly decreased in various types of leukemia including ones with MLL rearrangement." (PMID 34372899, 2021). "Thus, HDAC7 has the unique function to promote the growth of human erythroid leukemia cells by inhibiting their terminal maturation." (PMID 39277669, 2024). "However, conceptualizing the role of HDACs in leukemia as inducers of malignant transformation would be a too simplistic view, given that some histone deacetylases, such as HDAC7, carry out an opposite function." (PMID 32102485, 2020). "Next we wondered whether the expression of HDAC7 partners could be deregulated in leukemia and lymphoma cells expressing HDAC7." (PMID 25675295, 2015). "Given that HDAC7 is a transcriptional repressor, we wondered whether its expression could lead to the repression of key oncogenes in leukemia and lymphoma." (PMID 25675295, 2015). "Consistent with the data in DepMap, HDAC7 depletion suppressed the growth of erythroid leukemia cells but not that of non-erythroid leukemia cells." (PMID 39277669, 2024). "To verify the role of HDAC7 in human AEL, we then assessed the effect of HDAC7 depletion in two erythroid (F36P and TF-1) and two non-erythroid (THP-1 and KASUMI-1) leukemia cell lines." (PMID 39277669, 2024).
nasopharyngeal carcinoma (6 papers, 2020 to 2024). A carcinoma arising from the nasopharyngeal epithelium. "In nasopharyngeal carcinoma, miR-4465 expression can be modulated by histone deacetylase 7 (HDAC7)." (PMID 35892859, 2022). "However, the role and mechanism of HDAC7 in nasopharyngeal carcinoma (NPC) are still unclear." (PMID 32376822, 2020). "HDAC7 was reported to enhance EphA2 expression by downregulating miR-4465 expressing, showing a positive effect on tumour proliferation, migration, and invasion in nasopharyngeal carcinoma (NPC)." (PMID 34395273, 2021).
type 2 diabetes (6 papers, 2009 to 2022). "MC1568 is another HDAC7 inhibitor that improves insulin secretion from type 2 diabetes patients and rescues β-cell dysfunction caused by HDAC7 upregulation." (PMID 33042011, 2020). "We recently reported decreased DNA methylation and increased gene expression of HDAC7 in pancreatic islets from human donors with type 2 diabetes." (PMID 27796421, 2017). "Using microarray techniques, we recently found decreased DNA methylation and increased expression of HDAC7 in pancreatic islets from donors with type 2 diabetes, supporting a possible role for this enzyme in beta cell dysfunction and diabetes." (PMID 27796421, 2017). "It has also been reported recently that HDAC7 expression is increased in the pancreatic islets of type 2 diabetic patients and the expression of Tcf7l2 is promoted independently of histone acetylation to suppress insulin secretion." (PMID 28886131, 2017). "HDAC7A (histone deacetylase 7A) was also found to have a reduced expression in muscle from type 2 diabetes patients (FC = −1.54)." (PMID 19668377, 2009). "Our study supports HDAC7 inhibitors as a therapeutic option for the treatment of type 2 diabetes." (PMID 27796421, 2017). "Using RNA sequencing, we found increased HDAC7 expression in pancreatic islets from donors with type 2 diabetes compared with non-diabetic controls, confirming our previous finding." (PMID 27796421, 2017).
hepatocellular carcinoma (5 papers, 2020 to 2025). A malignant tumor that arises from hepatocytes. "Genetic analyses have also revealed an association between HDAC7 and hepatocellular carcinoma (HCC)." (PMID 35303381, 2023). "Whereas HDAC7, and to a lesser extent HDAC4, appear to repress HBV transcription, HDAC5 upregulated HBV capsid abundance and supported enhanced HBV biosynthesis in both hepatoma and nonhepatoma cells." (PMID 32822428, 2020).
non-small cell lung carcinoma (5 papers, 2020 to 2025). A group of at least three distinct histological types of lung cancer, including non-small cell squamous cell carcinoma, adenocarcinoma, and large cell carcinoma. "Based on these findings, which suggested the oncogenic role of HDAC7, our study in non-small cell lung cancer (NSCLC) confirmed that HDAC7 deacetylated β-catenin and facilitated its nuclear import and activated FGF18 expression by binding to TCF434." (PMID 39990668, 2025). "Although the precise mechanism of EPCs-induced neovascularization remains poorly understood, recent studies in non-small-cell lung carcinoma (NSCLC) demonstrated a key role of histone deacetylase 7 (HDAC7) in the regulation of angiogenic genes." (PMID 32775327, 2020). "Furthermore, our research group recently found that HDAC7 increased SNAIL protein levels by regulating fibroblast growth factor 18 (FGF18) in non-small cell lung cancer." (PMID 35595735, 2022).
autoimmune disease (4 papers, 2018 to 2025). A disorder resulting from loss of function or tissue destruction of an organ or multiple organs, arising from humoral or cellular immune responses of the individual to their own tissue constituents. "In humans, mutations in HDAC7, as well as in other genes that regulate it, are also associated with autoimmune disorders of the digestive tract and liver." (PMID 29664401, 2018). "Given its significant impact on inflammatory processes, HDAC7 has emerged as a potential therapeutic target in inflammatory and autoimmune diseases." (PMID 41229730, 2025). "Remarkably, restoring normal levels of these cells in the HDAC7-ΔP animals reduces the symptoms of their autoimmune diseases, even though the mice are still carrying the T cells that have escaped selection and can attack healthy tissues." (PMID 29664401, 2018). "Moreover, HDAC7 and many of its transcriptional targets are human risk loci for IBD and PSC, autoimmune diseases that strikingly resemble the disease we observe in HDAC7 gain-of-function in mice." (PMID 29664401, 2018). "To gain a better understanding of the significance of this overlap, we evaluated the 81 risk loci that were regulated by HDAC7 with respect to regulation by PLZF, differential expression in iNKT cells vs. Tconv, functional role in iNKT cell development, and functional role in autoimmune disease." (PMID 29664401, 2018). "However, the importance of HDAC7 in the positive selection of T cells in the thymus and TCR repertoire formation and therefore T cell development makes HDAC7 an undesirable target for the treatment of autoimmune diseases." (PMID 30792714, 2019).
Autoimmunity (4 papers, 2018 to 2023). The occurrence of an immune reaction against the organism's own cells or tissues. "It was therefore hypothesised that this genetic alteration in HDAC7 predisposes to autoimmunity; however, a causative link remains to be established." (PMID 35303381, 2023). "While this may indicate the importance of NR4A1/NR4A3 in clonal deletion, the cause of autoimmunity in this model is unclear, especially since these HDAC7 mutants demonstrated a generalized suppressive impact on the negative selection transcriptional program and impaired generation of Tregs." (PMID 33597928, 2020). "This suggests that phosphorylation of HDAC7 plays a crucial role in determining cell fate, particularly iNKT cell development and survival, with this being important in limiting autoimmunity and inflammatory disease." (PMID 35303381, 2023). "In phosphorylation‐defective Hdac7 mutant mice, where Hdac7 localised in the nucleus of developing thymocytes, iNKT cell survival was compromised and mice developed autoimmunity." (PMID 35303381, 2023). "More recently, a mechanistic study in mice revealed that perturbations in Hdac7 function can contribute to autoimmunity and a phenotype resembling inflammatory bowel disease (IBD) by altering CD4/CD8 DP thymocyte and iNKT cell development." (PMID 35303381, 2023). "Experiments performed in vivo on mice showed that HDAC7-ΔP TG mice developed lethal multi-organ autoimmunity, manifesting with lethal exocrine pancreatitis and visceral auto-aggression." (PMID 35887172, 2022). "In our earlier studies, we found that that HDAC7-ΔP-mediated autoimmunity is dominantly transferable in mixed BM chimeras if a 5-fold excess of HDAC7-ΔP-derived bone marrow is used." (PMID 29664401, 2018). "We earlier reported that HDAC7-ΔP mice develop spontaneous tissue-specific autoimmunity, with about 80% developing obliterative exocrine pancreatitis and concomitant T-cell infiltration in stomach, liver and small intestine within eight months." (PMID 29664401, 2018). "We thus set out to determine if restoring iNKT cells could alter the course of HDAC7-ΔP–induced autoimmunity." (PMID 29664401, 2018). "It was indicated that the impaired phosphorylation pathway of HDAC7 made it unable to shuttle into the cytoplasm during T-cell development, and as a result, the negative selection process was disrupted which could lead to autoimmunity." (PMID 35887172, 2022). "The striking parallel between these human syndromes and the autoimmunity observed in HDAC7-ΔP transgenic mice suggested to us a connection between HDAC7 and these types of autoimmunity that goes beyond simply blocking thymic negative selection." (PMID 29664401, 2018). "We report that Histone Deacetylase 7 (HDAC7) controls the thymic effector programming of Natural Killer T (NKT) cells, and that interference with this function contributes to tissue-specific autoimmunity." (PMID 29664401, 2018). "While engraftment at these ratios produced comparable populations of WT and HDAC7-ΔP Tconv in peripheral tissues, we did not assess the reconstitution of the iNKT compartment in those studies, leaving open the possibility that there was an uncharacterized recessive component to the autoimmunity." (PMID 29664401, 2018).
esophageal squamous cell carcinoma (4 papers, 2022 to 2025). Esophageal squamous cell carcinoma (ESCC) is a type of esophageal carcinoma (EC) that can affect any part of the esophagus, but is usually located in the upper or middle third. "Melatonin inhibits the growth of esophageal squamous cell carcinoma by suppressing histone deacetylase 7 (HDAC7)." (PMID 40756978, 2025). "Our previous study in esophageal squamous cell carcinoma (ESCC) showed that HDAC7 overexpression promoted ESCC cell growth and c-Myc expression." (PMID 39990668, 2025).
lung adenocarcinoma (4 papers, 2023 to 2026). A carcinoma that arises from the lung and is characterized by the presence of malignant glandular epithelial cells. "On the other hand, DNMT3Aa induces malignant transformation of lung adenocarcinoma cells by induction of the level of HDAC7 with concomitant increase of ZEB1 and c-Myc." (PMID 40764968, 2025).
Stroke (4 papers, 2025). Sudden impairment of blood flow to a part of the brain due to occlusion or rupture of an artery to the brain. "HDAC7, a class II histone deacetylase, has been implicated in various cellular processes including cell differentiation and survival, making it a critical target in stroke intervention." (PMID 40109665, 2025). "HDAC7 has been found to increase the astrocytic expression of inflammatory cytokines, supporting the hypothesis that HDAC7 is involved in stroke progression." (PMID 40867143, 2025). "In young mice, Hdac7 mRNA expression was significantly decreased in the ipsilateral region following photothrombotic stroke, and its expression showed a strong negative correlation with Tlr4." (PMID 40867143, 2025).
systemic sclerosis (4 papers, 2021 to 2024). A chronic disorder, possibly autoimmune, marked by excessive production of collagen which results in hardening and thickening of body tissues. "HDAC7 has also been shown to regulate collagen and other ECM in systemic sclerosis fibroblasts and siRNA mediated depletion of HDAC7 reduced ECM in these cells." (PMID 36864460, 2023). "A study of histone modification in systemic sclerosis (SS) patients showed that global acetylation of histone H4 was upregulated in B cells, while HDAC2 and HDAC7 were significantly downregulated." (PMID 35274786, 2022). "Silencing of HDAC7 was reported to attenuate cytokine-induced collagen I and collagen III production in primary fibroblasts from systemic sclerosis (SSc) patients." (PMID 34011384, 2021).
cardiac hypertrophy (3 papers, 2020 to 2024). "In the pathway for the role of NFAT in cardiac hypertrophy, histone deacetylase 7 and NFATc4 were both hypermethylated." (PMID 35336913, 2022). "However, HDAC5 was shown to play an integral role in cardiac development, suppression of oxidative stress, and heart hypertrophy, while HDAC7 maintained vascular integrity during early mouse heart development and participated in endothelial cell function." (PMID 32650632, 2020).
choroidal melanoma (3 papers, 2023 to 2025). Malignant tumor of melanocytes of the choroid. "In choroidal melanoma, HDAC7/c-Myc signalling pathway activity was confirmed to enhance tumour cell proliferation and metastasis." (PMID 39990668, 2025).
chronic lymphocytic leukemia (3 papers, 2018 to 2025). "In macrophages from chronic lymphocytic leukemia patients, HDAC7 knockdown or inhibition enhances macrophages phagocytic responses by activating Bruton’s tyrosine kinase." (PMID 39806423, 2025).
depression (3 papers, 2020 to 2025). "Exploration of manipulating HDAC7 on patterns of gene expression will facilitate to provide new insight into the possible mechanisms underlying depression." (PMID 33574772, 2020). "Observation of any degree of variation in social interaction scores that may be correlated with HDAC7 expression in NAc will confirm the function of HDAC7 in the regulation of depression." (PMID 33574772, 2020). "Limited studies have been conducted on the function of HDAC7 in depression." (PMID 33574772, 2020). "Moreover, we found that chronic social defeat stress in mice resulted in the reduction in HDAC7 levels in the NAc, which provided a new insight for the potential mechanism involved in depression." (PMID 33574772, 2020). "However, as an essential member of class II HDACs, the function of HDAC7 in depression is unclear." (PMID 33574772, 2020). "HDAC7 might be a promising therapeutic target for depression." (PMID 33574772, 2020). "Therefore, HDAC7 may be a promising therapeutic target for curing depression." (PMID 33574772, 2020).
diabetes (3 papers, 2017 to 2025). "These experiments support the development of a HDAC7-specific inhibitor for potential use in the treatment of diabetes." (PMID 27796421, 2017). "Importantly, insulin secretion was restored when Hdac7-overexpressing beta cells were treated with HDAC inhibitors, supporting the use of such compounds in the treatment of diabetes." (PMID 27796421, 2017). "Although these studies imply that increased HDAC levels may contribute to diabetes via hyperglycaemia and cytokine-induced toxicity, they did not identify HDAC7 as a target for the disease." (PMID 27796421, 2017).
diffuse large B-cell lymphoma (3 papers, 2015 to 2025). "Overall, HDAC7 was significantly upregulated in tumor tissues relative to adjacent normal tissues, with the highest expression observed in thymoma (THYM) and diffuse large B-cell lymphoma (DLBC)." (PMID 41444923, 2025).
ischemic stroke (3 papers, 2025). A stroke disorder caused by obstruction of blood flow to the brain, due to thrombotic (local blood clot formation) or embolic (due to a blood clot or other material traveling from another site) event. "The two-way factorial ANOVA analysis showed that Hdac7 mRNA expression was affected by ischemic stroke and tended to be influenced by the interaction between ischemic stroke and aging." (PMID 40867143, 2025). "The gene expression analysis conducted in this study provides compelling evidence for the role of specific genes, such as HDAC7, in the pathophysiology of ischemic stroke and the therapeutic effects of electroacupuncture." (PMID 40109665, 2025). "Initial validation suggested that HDAC7 was aberrantly overexpressed in the ischemic stroke group, whereas electroacupuncture intervention had a suppressive effect on the fluorescence intensity and protein level of HDAC7." (PMID 40109665, 2025). "The Friends analysis revealed that HDAC7 exhibited a robust correlation with other super enhancer-driven genes and may therefore play a pivotal role in ischemic stroke." (PMID 40109665, 2025). "The histone deacetylase HDAC7, upregulated by super-enhancers, is highly expressed in MCAO model mice according to the RNA-seq data, leading to the preliminary hypothesis that HDAC7 could be a pivotal pathogenic factor in ischemic stroke." (PMID 40109665, 2025). "Moreover, electroacupuncture may address ischemic stroke by modulating the expression of HDAC7, which is influenced by super-enhancers." (PMID 40109665, 2025).
liver cancer (3 papers, 2022 to 2025). An epithelial or non-epithelial malignant neoplasm that arises from the liver. "To further investigate the role of HDAC7 in liver cancer, we used GEPIA to analyze HDAC7 expression in liver cancer cases from TCGA." (PMID 39736396, 2025). "Taken together, these results indicated that HDAC7 as a potential prognostic marker for liver cancer, and LukS-PV can downregulate the high expression of HDAC7 by targeting C5aR1 in HCC cells." (PMID 39736396, 2025). "HDAC7 is reportedly highly expressed and play cancer-promoting roles in tumor cells, such as breast and lung; however, there have been few studies of HDACs in liver cancer." (PMID 39736396, 2025). "In addition, to determine whether LukS-PV inhibited liver cancer progression by downregulating HDAC7–Wnt/β-catenin signaling in vivo." (PMID 39736396, 2025). "Next, we investigated the relationship between the expression levels of C5aR1, HDAC7, and CTNNB1 in liver cancer cases from TCGA database." (PMID 39736396, 2025). "Among them, HDAC7, HDAC4, SIRT7, KAT2A, and HDAC11 were the top five most upregulated genes, indicating that the expression of deacetylation-related genes played a dominant role in liver cancer compared with acetylation-related genes." (PMID 36124029, 2022). "However, the effect of HDAC7 on the acetylation of β-catenin in liver cancer had not been reported." (PMID 39736396, 2025).
lymphoma (3 papers, 2015 to 2026). A malignant (clonal) proliferation of B- lymphocytes or T- lymphocytes which involves the lymph nodes, bone marrow and/or extranodal sites. "First, we report the loss of HDAC7 expression in pro-B-ALL patients and in established B-ALL and B lymphoma cell lines." (PMID 25675295, 2015). "Similar to the results obtained with leukemic cells, the expression of HDAC7 in Namalwa cells markedly interfered with the growth of lymphomas." (PMID 25675295, 2015). "Next we tested whether HDAC7 expression could also be deregulated in lymphomas." (PMID 25675295, 2015).
mucoepidermoid carcinoma (3 papers, 2017 to 2024). A carcinoma morphologically characterized the presence of cuboidal mucous cells, goblet-like mucous cells, squamoid cells, cystic changes, and a fibrotic stromal formation. "HDAC7 knockdown in salivary mucoepidermoid carcinoma (MEC) cells led to growth suppression by G2/M arrest and the promotion of apoptosis and autophagy." (PMID 38702756, 2024).